CRK (CRK proto-oncogene, adaptor protein)
Description:
Involved in cell branching and adhesion mediated by BCAR1-CRK-RAPGEF1 signaling and activation of RAP1. [Isoform Crk-II]: Regulates cell adhesion, spreading and migration. Mediates attachment-induced MAPK8 activation, membrane ruffling and cell motility in a Rac-dependent manner. Involved in phagocytosis of apoptotic cells and cell motility via its interaction with DOCK1 and DOCK4. May regulate the EFNA5-EPHA3 signaling (By similarity).
Synonyms: CRKII; p38
Tractability: Antibody: UniProt places it where antibodies can reach, with medium confidence; its Gene Ontology location is reachable by antibodies, with medium confidence; the Human Protein Atlas places it where antibodies can reach. PROTAC: its protein half-life has been measured; a small molecule that binds it is known.
Gene: Protein-coding gene on chromosome 17 (1,420,689 to 1,463,162, reverse strand). Ensembl gene ENSG00000167193.
Subcellular location: Cytoplasm; Cell membrane
Subcellular location (Human Protein Atlas): Plasma membrane; Actin filaments; Basal body; Nucleoplasm
Pathways (Reactome):
Signal Transduction: ARMS-mediated activation; Downstream signal transduction; MET activates RAP1 and RAC1; MET receptor recycling; PTK6 Regulates RHO GTPases, RAS GTPase and MAP kinases; VEGFA-VEGFR2 Pathway; p130Cas linkage to MAPK signaling for integrins
Immune System: Regulation of actin dynamics for phagocytic cup formation; Regulation of signaling by CBL
Disease: FCGR3A-mediated phagocytosis
Gene Ontology:
Molecular function: kinase binding; phosphotyrosine residue binding; protein binding; protein phosphorylated amino acid binding; protein tyrosine kinase binding; SH2 domain binding; SH3 domain binding; signaling adaptor activity; receptor tyrosine kinase binding; cytoskeletal protein binding; enzyme binding; insulin-like growth factor receptor binding; protein domain specific binding; protein-macromolecule adaptor activity; scaffold protein binding; signaling receptor complex adaptor activity; ubiquitin protein ligase binding
Biological process: actin cytoskeleton organization; ephrin receptor signaling pathway; negative regulation of cell motility; negative regulation of wound healing; positive regulation of substrate adhesion-dependent cell spreading; regulation of actin cytoskeleton organization; regulation of cell shape; regulation of intracellular signal transduction; regulation of signal transduction; cell adhesion; cell migration; enzyme-linked receptor protein signaling pathway; regulation of transcription by RNA polymerase II; cell population proliferation; cellular response to endothelin; cellular response to insulin-like growth factor stimulus; cellular response to nerve growth factor stimulus; cellular response to nitric oxide; cellular response to transforming growth factor beta stimulus; negative regulation of natural killer cell mediated cytotoxicity; positive regulation of JNK cascade; positive regulation of Rac protein signal transduction; positive regulation of smooth muscle cell migration; postsynaptic specialization assembly; protein localization to membrane; and 7 more
Cellular component: cytoplasm; cytosol; extracellular exosome; protein-containing complex; membrane; nucleus; protein complex involved in cell adhesion; actin cytoskeleton; neuromuscular junction; plasma membrane
Genetic constraint (gnomAD): Loss-of-function variants: 4 observed, 27.17 expected, observed/expected ratio (o/e) 0.15, 90% interval 0.072 to 0.34. The upper end of that interval is the gene's LOEUF score, 0.34, which puts it in group 1 of 6, group 1 being the genes least tolerant of losing a copy. Missense variants: 274 observed, 384.98 expected, observed/expected ratio (o/e) 0.71, 90% interval 0.64 to 0.79. Synonymous variants: 153 observed, 159.37 expected, observed/expected ratio (o/e) 0.96, 90% interval 0.84 to 1.1.
Homologues: Orthologues: chimpanzee CRK (100% identical), macaque CRK (100% identical), mouse Crk (99% identical), pig CRK (99% identical), rat Crk (92% identical), tropical clawed frog crk (85% identical), guinea pig CRK (80% identical), zebrafish crk (74% identical), Drosophila melanogaster Crk (45% identical), Caenorhabditis elegans ced-2 (31% identical). Paralogues in human: CRKL (61% identical).
Diseases named in the same sentence as CRK in open-access papers:
CRK is named in the same sentence as 72 diseases in open-access papers, as found by Europe PMC text mining. Sharing a sentence is not in itself a finding about the gene and the disease. The quoted sentences say what the papers report.
breast cancer (17 papers, 2006 to 2026). A primary or metastatic malignant neoplasm involving the breast. "The CRK adaptors are also linked to breast cancer anti-estrogen resistance proteins BCAR1 and BCAR3, which also associate with each other." (PMID 37686522, 2023). "The fourth eigenspace emphasizes protein CRK-associated substrate (docid: 1036799), which is a breast cancer anti-estrogen resistance protein, and its encoding DNA sequences and interactions." (PMID 16480496, 2006). "The top 6 cancer types with 5 and higher cases of CRK transcript amplification include ovarian cancer, endometrial cancer, prostate cancer, melanoma, breast cancer, and sarcoma." (PMID 33801580, 2021). "On the other hand, miR-126 was shown to function as a tumor suppressor targeting on CRK in gastric cancer, mammary cancer and non-small cell lung carcinoma cell lines." (PMID 23285182, 2012). "Interestingly, it has been shown that miR-126 directly regulates the expression of CRK in non-small cell lung carcinoma, gastric and breast cancer and one would expect PDAC to exhibit high expression of CRK if this oncogene is repressed by miR-126 in pancreas." (PMID 22384141, 2012).
non-small cell lung carcinoma (8 papers, 2011 to 2025). A group of at least three distinct histological types of lung cancer, including non-small cell squamous cell carcinoma, adenocarcinoma, and large cell carcinoma. "MiR-126 was found to inhibit cell adhesion, migration and invasion partially through the suppression of CRK in an in vitro model of non-small-cell lung carcinoma." (PMID 21533124, 2011).
gastric cancer (6 papers, 2012 to 2024). A primary or metastatic malignant neoplasm involving the stomach. "More interestingly, significant interactions between the CRK genetic polymorphism and four phytoestrogen biomarkers, genistein, daidzein, equol and enterolactone, modified gastric cancer risk." (PMID 22383989, 2012). "This study shows SRC, c-MET, and CRK genetic variants can be susceptible genetic factors for the development of gastric cancer by controlling signals through the CagA transduction pathways." (PMID 22383989, 2012). "Risk allele of CRK rs7208768 had a significantly increased risk for gastric cancer at low phytoestrogen levels (p interaction<0.05)." (PMID 22383989, 2012). "Our findings suggest that SRC, c-MET and CRK play a key role in gastric carcinogenesis by modulating CagA signal transductions and interaction between CRK gene and phytoestrogens modify gastric cancer risk." (PMID 22383989, 2012). "To evaluate this hypothesis, we genotyped 137 SNPs in seven candidate genes and demonstrated that genetic variants of SRC (rs6122566 and rs6124914), c-MET (rs41739) and CRK (rs7208768) were significantly associated with gastric cancer risk." (PMID 22383989, 2012). "In the extension phase, two SNPs, rs6122566 and rs6124914, in SRC gene and rs7208768 in CRK remained significantly associated with an increased risk for gastric cancer (OR = 4.01, [95% CI: 1.62–9.96]; OR = 1.30, [95% CI: 1.00–1.70]; OR = 1.33, [95% CI: 1.08–1.64], respectively)." (PMID 22383989, 2012). "Additionally, an interactive effect of CRK genetic polymorphism, rs7208768, and four phytoestrogen biomarkers, genistein, daidzein, equol and enterolactone on gastric cancer risk were analyzed." (PMID 22383989, 2012). "Our findings also support the genetic potential of CRK rs7208768 on the development of gastric cancer and both genetic and cellular magnitude of CRK." (PMID 22383989, 2012). "Considering CRK is the major upstream molecule of ERK activation, the risky genetic variants of CRK to activate the ERK signaling can be blocked by phytoestrogens, and mediate the development of gastric cancer." (PMID 22383989, 2012). "Moreover, SRC rs6124914, c-MET rs41739 and CRK rs7208768 showed significant gene-dose effects for gastric cancer in both analyses." (PMID 22383989, 2012). "A similar analysis using cBioPortal of a smaller subset for lung, breast, and gastric cancer patients combined did not exhibit any apparent difference in overall survival among the patients with amplification of CRK and CRKL transcripts (data not shown)." (PMID 33801580, 2021). "Though additional stratified analyses were also conducted to detect an interaction between CagA seropositivity and each gene effect for gastric cancer risk, interactions were not significant in any of the three genes, SRC, c-MET and CRK (data not shown)." (PMID 22383989, 2012). "Because some CagA interacting molecules such as SHP-2, CRK and CSK are only able to respond with phosphorylated CagA, SRC can be more important in influencing other's cellular functions and inducing development of gastric cancer." (PMID 22383989, 2012).
lung carcinoma (6 papers, 2015 to 2023). "Crawford discovered that miR-126 can suppress lung cancer invasion by directly targeting CRK, and Liu reported that miR-126 suppresses the expression of VEGF-A, inhibiting cancer cell growth." (PMID 28536606, 2016).
pancreatic cancer (4 papers, 2014 to 2023). "MiR-126 is also the target of other important oncogenes such as KRAS and CRK in pancreatic cancer Therefore, overexpression of miR-126 in SPNs-treated cells can be a reason for inhibition of MIA PaCa-2 proliferation and migration." (PMID 32489562, 2020). "CRK-II, an adaptor protein from cytoskeletal signalling pathways, has been shown to promote cell migration when expressed in human pancreatic carcinoma cells." (PMID 25478005, 2014).
epilepsy (3 papers, 2018 to 2021). A brain disorder characterized by episodes of abnormally increased neuronal discharge resulting in transient episodes of sensory or motor neurological dysfunction, or psychic dysfunction. "In the deletion region, the YWHAE and CRK genes on the telomeric end of chromosome 17p have been considered as epilepsy-causing genes in previous clinical reports, and the deletion was interpreted as pathogenic." (PMID 34055682, 2021). "Patients with chromosome 17p13.3 deletions involving CRK and YWHAE but not PAFAH1B1 were reported, and they showed generalized epilepsy, growth retardation, and macrocephaly, implicating Crk deficiency in epilepsy." (PMID 35053800, 2021). "As with lissencephaly, YWHAE, CRK, and PAFAH1B1 have complicated roles in epilepsy." (PMID 29628935, 2018). "Thus, YWHAE, CRK, and PAFAH1B1 are critical genes involved in epilepsy." (PMID 29628935, 2018). "Two patients with deletions of YWHAE and CRK, but not PAFAH1B1, were described as having macrocephaly, epilepsy, and non-specific changes in white matter, among other clinical features." (PMID 29628935, 2018).
leukemia (3 papers, 2019 to 2025). A malignant (clonal) hematologic disorder, involving hematopoietic stem cells and characterized by the presence of primitive or atypical myeloid or lymphoid cells in the bone marrow and the blood. "Importantly, in our GWAS, which was also adjusted for white blood cell counts, we found association signals near genes involved in leukaemia and lymphoma development (CRK, BAK1, CDK6, MDFIC, BIK) as well as a significant enrichment of pathways related to immune cell proliferation." (PMID 33385171, 2021). "CRK, an oncogene involved in cellular transformation, is currently being investigated as a therapeutic target in leukemia." (PMID 39940906, 2025).
Intellectual disability (2 papers, 2020 to 2025). "Duplications on the 17p13.3 chromosomal region, impacting genes such as YWHAE, CRK, and PAFAH1B1, are established risk factors for various neuropsychiatric conditions, including intellectual disability, autism spectrum disorder, and behavioral problems." (PMID 40642416, 2025). "Duplications on 17p13.3 affecting YWHAE, CRK, and/or PAFAH1B1 have been identified as susceptibility factors for intellectual disability, hypotonia, autism spectrum disorders, behavioral disturbances, brain malformations, dysmorphic facial features, and limb anomalies." (PMID 40642416, 2025).
Lissencephaly (2 papers, 2018). A spectrum of malformations of cortical development caused by insufficient neuronal migration that subsumes the terms agyria, pachygyria and subcortical band heterotopia. "Creation of a Crk/Pafah1b1 double knockout could help determine if deletion of these genes contributes to the lissencephaly phenotype in a dose-dependent manner, as this seems to be the case when CRK and YWHAE are deleted together in humans." (PMID 29628935, 2018).
melanoma (2 papers, 2021 to 2023). A malignant, usually aggressive tumor composed of atypical, neoplastic melanocytes. "Unlike miR-17, 18a, 182, 210, and 214, whose increased expression promotes melanoma, upregulation of miR-126 in human cells has anti-melanoma function through its modulation of v-crk sarcoma virus CT10 oncogene homolog (CRK), a regulator of migration and adhesion." (PMID 34067095, 2021).
renal cell carcinoma (2 papers, 2020 to 2022). "The NR5A1-derived tumors showed 657 unique proteins that participate in Renal cell carcinoma (CRK, ELOB and PAK3) and Homologous recombination (ATM, BRCC3 and MRE11) among others." (PMID 33261069, 2020).
cerebellar pilocytic astrocytoma (1 paper, 2013). A WHO Grade 1 astrocytoma which arises in the cerebellum. "Hypothalamo-chiasmatic pilocytic astrocytomas and cerebellar pilocytic astrocytomas have a distinctive gene signature and several differential expressed genes (ICAM1, CRK, CD36, and IQGAP1) are targets for available drugs: fluvastatin and/or celecoxib." (PMID 24252689, 2013).
cervical cancer (1 paper, 2021). A primary or metastatic malignant neoplasm involving the cervix. "The most prominent targets of these miRs are PTEN, CRK proto-oncogene, adaptor protein (CRK), SOD2, TXNIP IGF1R, BCL2 apoptosis regulator (BCL2), and FOXK1, which play a crucial role in cervical cancer progression." (PMID 33802524, 2021).
colon cancer (1 paper, 2012). "Several studies have indicated that overexpression of CRK is associated with various types of human cancers including lung, gastric and colon cancer." (PMID 22383989, 2012).
fungal infection (1 paper, 2023). "This suggests that although Tha-Lr14a may not possess direct recognition or resistance to Pt isolate 95037, it still activates alternative defense pathways involving these CRK genes to counteract the detrimental effects of the virulent fungal infection." (PMID 37631144, 2023).
Inguinal hernia (1 paper, 2020). Protrusion of the contents of the abdominal cavity through the inguinal canal. "We discovered that PIK3R1, PTPN11, TGFBR1, CDC42, SOS1, and KRAS were the most essential inguinal hernia-causative proteins and UBC, GRB2, CTNNB1, HSP90AA1, CBL, PLCG1, and CRK were listed as the most commonly-involved downstream proteins." (PMID 31910207, 2020).
lung tumors (1 paper, 2018). "However, expression levels of downstream markers TPM-1, TOM-1, CRK, fibulin-2, MIF, and EFNA-3 were greater in the lung tumors than in non-tumor specimens only in patients without COPD." (PMID 29371906, 2018).
macrosomia (1 paper, 2019). "Microduplications at 17p13.3, involving the YWHAE and CRK genes, similarly to our patient, are associated with macrosomia in the majority of cases." (PMID 31749829, 2019).
omphalocele (1 paper, 2025). Omphalocele is an embryopathy classified in the group of abdominal celosomias and is characterized by a large hernia of the abdominal wall, centered on the umbilical cord, in which the protruding viscera are protected by a sac. "The findings of this study indicate that PAFAH1B1, YWHAE and CRK are associated with major phenotypes of 17p13.3, and RTN4RL1 may be involved in white matter changes and HIC1 might contribute to the occurrence of omphalocele." (PMID 40390087, 2025). "While PAFAH1B1, YWHAE and CRK are associated with major phenotypes of 17p13.3, RTN4RL1 may be involved in white matter changes and HIC1 might contribute to the occurrence of omphalocele." (PMID 40390087, 2025).
osteosarcoma (1 paper, 2011). A usually aggressive malignant bone-forming mesenchymal neoplasm, predominantly affecting adolescents and young adults. "CDK 9 overexpression also increased proliferation of human osteosarcoma cell line U20S2, while CRK, CDK9, DCAF7, NEK6, GNB1, SPOP, and WW2 also increased proliferation in mouse fibroblasts." (PMID 21629697, 2011).
psychomotor delay (1 paper, 2012). "Class II microduplications always involve PAFAH1B1 and may extend to CRK and YWHAE and have been associated to hypotonia, mild developmental, and psychomotor delay." (PMID 23035971, 2012).
schizophrenia (1 paper, 2022). A major psychotic disorder characterized by abnormalities in the perception or expression of reality. "Furthermore, genes (including GRM1, ADK, CACNA1C, CRK and GAB1) which the most significant SNPs of the five first-generation antipsychotics specific analyses are located within were both associated with the schizophrenia and heart diseases." (PMID 35136033, 2022).
Wilms tumor (1 paper, 2022). An embryonal neoplasm characterized by the presence of epithelial, mesenchymal, and blastema components. "Taken together, MEG8 regulates pathogenesis of Wilms tumor through miR-23a-3p/CRK axis." (PMID 36114498, 2022). "Similarly, expression of MEG8 has been found to be elevated in Wilms tumor cells, parallel with up-regulation of CRK and down-regulation of miR-23a-3p." (PMID 36114498, 2022).